STEAP1B (STEAP family member 1B)
Synonyms: LOC401312
Tractability: Antibody: UniProt predicts a signal peptide or a membrane-spanning region; its Gene Ontology location is reachable by antibodies, with medium confidence.
Gene: Protein-coding gene on chromosome 7 (22,417,857 to 22,727,613, reverse strand). Ensembl gene ENSG00000105889.
Subcellular location: Membrane
Gene Ontology:
Molecular function: protein binding
Cellular component: endosome; plasma membrane; membrane
Genetic constraint (gnomAD): Loss-of-function variants: 12 observed, 25.25 expected, observed/expected ratio (o/e) 0.48, 90% interval 0.3 to 0.77. The upper end of that interval is the gene's LOEUF score, 0.77, which puts it in group 3 of 6, group 1 being the genes least tolerant of losing a copy. Missense variants: 230 observed, 264.38 expected, observed/expected ratio (o/e) 0.87, 90% interval 0.78 to 0.97. Synonymous variants: 80 observed, 96.55 expected, observed/expected ratio (o/e) 0.83, 90% interval 0.69 to 1.
Homologues: Orthologues: macaque STEAP1 (92% identical), chimpanzee STEAP1B (89% identical), pig STEAP1 (85% identical), chimpanzee STEAP1B (84% identical), dog STEAP1 (84% identical), rabbit STEAP1 (84% identical), guinea pig Steap1 (82% identical), rat Steap1 (80% identical), mouse Steap1 (78% identical), tropical clawed frog steap1 (52% identical). Paralogues in human: STEAP1 (92% identical), STEAP2 (46% identical), STEAP3 (42% identical), STEAP4 (36% identical).
Diseases named in the same sentence as STEAP1B in open-access papers:
STEAP1B is named in the same sentence as 6 diseases in open-access papers, as found by Europe PMC text mining. Sharing a sentence is not in itself a finding about the gene and the disease. The quoted sentences say what the papers report.
prostate carcinoma (2 papers, 2014 to 2015). A carcinoma that arises from epithelial cells of the prostate gland. "Clarifying the regulation of STEAP1 as well as the expression and function of STEAP1B on cells may open novel strategies for diagnosis and treatment of prostate cancer." (PMID 25053991, 2014).
breast carcinoma (1 paper, 2024). "STEAP proteins include STEAP1‐4 and atypical STEAP1B; among them, STEAP1‐4 is lower expressed in breast cancer compared with normal tissues, and some people believe that STEAP1‐4 is a tumor suppressor of breast cancer." (PMID 39676279, 2024).
lung carcinoma (1 paper, 2025). "LOC401312, a five-exon lncRNA transcribed from the STEAP1B locus on chromosome 7, was functionally characterized through overexpression in A549 and H460 lung cancer cells, with qRT-PCR validation confirming robust transcriptional activation efficiency." (PMID 40565327, 2025).
cancer (1 paper, 2021). A tumor composed of atypical neoplastic, often pleomorphic cells that invade other tissues. "However, considering the similar structural features of STEAP1B with other family members, STEAP1B may play a role in different cancers, but experimental proof is still required." (PMID 34778263, 2021). "Up to now, there are no relevant reports regarding the function of STEAP1B in cancer." (PMID 34778263, 2021).
STEAP1B also shares sentences with these, for which no sentence is quoted: lung adenocarcinoma (1 paper); squamous cell carcinoma (1).